LRG1 (leucine rich alpha-2-glycoprotein 1)
Diseases named in the same sentence as LRG1 in open-access papers (continued):
Sharing a sentence is not in itself a finding about the gene and the disease.
sarcopenia (2 papers, 2024 to 2026). Progressive decline in muscle mass due to aging which results in decreased functional capacity of muscles. "We identified seven robust protein signatures (LRG1, CST3, TIMP1, C2, ITIH1, AMBP and LYZ) that showed consistent significant associations with sarcopenia components in both cohorts." (PMID 41782349, 2026). "Our study investigated the plasma proteome of individuals with age-related sarcopenia and identified 8 DEPs that showed promising predictive performance, including IGFBP2, PON3, LRG1, PRDX6, PTGDS, CD163, PRG4, and TRAJ17." (PMID 39725826, 2024).
Still’s disease (2 papers, 2016 to 2025). "LRG1 has also been suggested as promising biomarker in other disease entities, such as Still’s disease and in peptidomics studies." (PMID 27378305, 2016).
acute coronary syndrome (1 paper, 2024). Signs and symptoms related to acute ischemia of the myocardium secondary to coronary artery disease. "For instance, one study demonstrated that LRG1 is elevated in patients with acute coronary syndrome compared with healthy controls." (PMID 38742172, 2024).
acute lymphoblastic leukemia (1 paper, 2022). Leukemia with an acute onset, characterized by the presence of lymphoblasts in the bone marrow and the peripheral blood. "In hematological malignancies, LRG1 was elevated in the serum of pediatric acute lymphoblastic leukemia at the time of diagnosis." (PMID 35371990, 2022).
Allergy (1 paper, 2016). An allergy is an immune response or reaction to substances that are usually not harmful. "Therefore, LRG1 could be a key regulatory factor of allergy, and its reduced release may contribute to the development of allergy." (PMID 27378305, 2016). "Since allergy is also an inflammatory and immunological disease, and LRG may play a role in it, we investigated the expression of LRG1 in allergic disorders and its potential cell origins in the present study." (PMID 27378305, 2016).
ANCA-associated vasculitis (1 paper, 2020). "Leucine-rich alpha-2-glycoprotein (Lrg1) is mitogenic to endothelial cells and promotes angiogenesis, and is regulated in ANCA-associated vasculitis." (PMID 33023023, 2020).
aneurysm (1 paper, 2009). Bulging or ballooning in an area of an artery secondary to arterial wall weakening. "We observed downregulation of the genes encoding kininogen (kng1), Apolipoprotein CI (Apoc1) and the neutrophil-associated leucine-rich alpha-2-glycoprotein 1 (Lrg1) amongst others, in aortas of mice resistant to aneurysm suggesting that they may be pathological genes." (PMID 19580648, 2009).
angina pectoris (1 paper, 2024). The symptom of paroxysmal pain consequent to MYOCARDIAL ISCHEMIA usually of distinctive character, location and radiation. "Second, this study only evaluated the clinical role of LRG1 in patients with STEMI, while it lacked investigation into other types of cardiovascular diseases (such as non-STEMI and angina pectoris)." (PMID 38742172, 2024).
ankylosing spondylitis (1 paper, 2020). An autoimmune chronic inflammatory disorder characterized by inflammation in the vertebral joints of the spine and sacroiliac joints. "In ankylosing spondylitis patients, IL-6 and LRG-1 were identified as biomarkers with concordance to disease severity." (PMID 31953524, 2020). "In the ankylosing spondylitis cohort, we discovered robust positive correlations of the disease-centric biomarkers LRG-1 and IL-6 with clinical severity." (PMID 31953524, 2020). "IL-6 and LRG-1 were identified as biomarkers with concordance to ankylosing spondylitis severity." (PMID 31953524, 2020).
arterial disease (1 paper, 2021). "LRG1 expression was higher in the endothelium of stenotic coronary arteries compared to non-stenotic coronary arteries, suggesting a potential role for LRG1 in endothelial homeostasis and arterial disease." (PMID 34291056, 2021).
autoimmune uveitis (1 paper, 2024). An autoimmune form of uveitis (disease). "Similarly, Lrg1 was found upregulated in diseased endothelium from inflamed retinal vessels in a mouse model of experimental autoimmune uveitis, suggesting a role for LRG1 in retinal inflammation and angiogenesis." (PMID 38745756, 2024).
Autoimmunity (1 paper, 2022). The occurrence of an immune reaction against the organism's own cells or tissues. "LRG1 is associated with several human diseases, including cancer, inflammatory disorders, autoimmunity and neurological diseases." (PMID 36591261, 2022).
benign ovarian tumors (1 paper, 2010). "LRG1 mRNA expression levels were about 2-fold higher in benign ovarian tumors and about 3-4 fold higher in ovarian serous cancers compared to normal ovaries." (PMID 20831812, 2010).
brain tumours (1 paper, 2022). "In support of LRG1 being a destabilizing factor in tumour vessels, Lrg1 upregulation was also observed in brain tumours characterized by a profoundly altered and permeable blood–brain barrier." (PMID 35062948, 2022).
cardiac ischemia (1 paper, 2023). "Our transcriptional data provide evidence that significantly higher levels of hypoxia-related and proangiogenic genes (HIF1a, VEGFA, FGF2, eNOS, SOX17, and LRG1) promote neovascularization at the site of increased cardiac ischemia." (PMID 36371548, 2023).
cardiomyopathy (1 paper, 2020). A disease of the heart muscle or myocardium proper. "Investigations of LRG1 and its related signaling pathways may offer novel therapeutic targets in cats with cardiomyopathy, and LRG1 also may have a role as an additional cardiac biomarker in cats." (PMID 32395893, 2020).
cataract (1 paper, 2021). Partial or complete opacity of the crystalline lens of one or both eyes that decreases visual acuity and eventually results in blindness. "Note that controls in this study were patients with cataracts, who were not necessarily representative of disease-free individuals, although our detection of LRG1 in these samples was consistent with published proteomic data." (PMID 34445590, 2021).
cholangiocarcinoma (1 paper, 2018). A carcinoma that arises from the intrahepatic biliary tree (intrahepatic cholangiocarcinoma) or from the junction, or adjacent to the junction, of the right and left hepatic ducts (hilar cholangiocarcinoma). "Carbohydrate antigen 19-9 (CA19-9), leucine-rich α2-glycoprotein (LRG1), interleukin 6 (IL6), pyruvate kinase M2 (PKM2), cytokeratin 19 fragment (CYFRA21.1) and mucin 5AC (MUC5AC) have reported utility for differentiating cholangiocarcinoma (CCA) from benign biliary disease." (PMID 29707118, 2018).
chronic cholecystitis (1 paper, 2011). "Biliary epithelium from a gallbladder showing chronic cholecystitis demonstrated negative staining for LRG1." (PMID 21970875, 2011).
chronic heart failure (1 paper, 2023). "LRG1 protein had a higher serum abundance in the group with MMVD stage C compared to the healthy/control group and the groups with MMVD stages B1 and B2, indicating its much bigger role in disease mechanisms with the development of chronic heart failure." (PMID 37108311, 2023).
clear cell ovarian cancer (1 paper, 2010). "In a separate set of 193 pre-surgical samples, LRG1 was higher in patients with serous or clear cell ovarian cancer (145.82 ± 65.99 ug/ml) compared to patients with benign gynecological diseases (82.53 ± 76.67 ug/ml, p < 0.0001)." (PMID 20831812, 2010). "Although our gene microarray data showed that LRG1 mRNA expression levels were greatest in low malignant potential tumors, the level of serum LRG1 protein in the LMP tumors was significantly lower than for both serous and clear cell ovarian cancer." (PMID 20831812, 2010).
colon adenocarcinoma (1 paper, 2020). "LRG1 expression can be induced by TNF-α, IL-6, and IL-22 in human colon adenocarcinoma cell line." (PMID 32249825, 2020).
diabetic neuropathy (1 paper, 2024). A chronic, pathological complication associated with diabetes mellitus, where nerve damages are incurred due to diabetic microvascular injury involving small blood vessels that supply these nerves, resulting in peripheral and/or autonomic nerve dysfunction. "Further research is needed to unravel the consequences of changes in LRG1 during the development and progression of diabetic neuropathy." (PMID 39845838, 2024). "Research on LRG1 in diabetic neuropathy remains very limited." (PMID 39845838, 2024).
dilated cardiomyopathy (1 paper, 2015). Cardiomyopathy which is characterized by dilation and contractile dysfunction of the left and right ventricles. "However, the molecular basis of LRG1 down-regulation in both mouse models remains to be resolved, which is vital for dissecting the mechanism of dilated cardiomyopathy pathogenesis." (PMID 28509980, 2015).
dyslipidemia (1 paper, 2023). "In addition, several studies have shown that LRG1 level is related to age and dyslipidemia." (PMID 37916147, 2023).
erectile dysfunction (1 paper, 2022). Persistent or recurrent inability to achieve or to maintain an erection during sexual activity. "Taken together, our results indicate that exogenous LRG1 treatment profoundly restores the decreased numbers of endothelial cells in cavernosum tissue and neurofilaments at DNBs, thereby ameliorating erectile dysfunction in STZ-induced diabetic mice." (PMID 35562586, 2022).
esophagus cancer (1 paper, 2021). "Combound biomarker of LRG1 and C-reactive protein and soluble interleukin-6 receptor could forecast the response to preoperative chemoradiotherapy in esophageal cancer patients." (PMID 35095520, 2021).
fungal keratitis (1 paper, 2025). "The role of LRG1 in immune cell regulation further emphasizes the complexity of host–pathogen interactions in fungal keratitis, as it could potentially influence both disease progression and therapeutic responses." (PMID 40521031, 2025).
Hypercalcemia (1 paper, 2024). An abnormally increased calcium concentration in the blood. "Multivariable analysis revealed that CRP level (P = 0.002), grade (P = 0.032), hypercalcemia (P = 0.023) and hemoglobin level (P = 0.037) were independent predictors of LRG1 levels." (PMID 38658967, 2024).
Hypoinsulinemia (1 paper, 2025). A decreased concentration of insulin in the blood. "In both the streptozotocin (STZ) model, where hypoinsulinemia is chemically induced, and in the Ins2Akita model, which develops it spontaneously due to a mutation in the insulin gene, we observed early induction of the secreted glycoprotein gene leucine-rich α-2-glycoprotein 1 (Lrg1)." (PMID 41124286, 2025).
intestinal cancer (1 paper, 2021). "Reports on the relationship between intestinal cancer and LRG1 have rapidly increased in the last 5 years." (PMID 35095520, 2021).
iron deficiency (1 paper, 2023). "In this study, we observed significant associations between several iron deficiency markers and LRG1." (PMID 37513518, 2023). "Overall, these previous reports indicate that both LRG1 and iron deficiency are implicated in regulating the HIF-1α pathway." (PMID 37513518, 2023). "Moreover, our study was carried out on a reasonably large sample size and several statistical tools were employed to robustly show the association between LRG1 and iron deficiency in children." (PMID 37513518, 2023). "In addition, our study investigated the association between LRG1 and iron deficiency in children, as establishing this association in a relatively healthy young population guarantees its independence from the complications commonly observed with adulthood iron deficiency." (PMID 37513518, 2023). "One of the strengths of our study is that it is one of the first studies to explore the association between LRG1 and iron deficiency as this association has not been extensively explored yet." (PMID 37513518, 2023). "However, the association between LRG1 and iron deficiency in children has not been well established." (PMID 37513518, 2023).
Left ventricular diastolic dysfunction (1 paper, 2023). Abnormal function of the left ventricule during left ventricular relaxation and filling. "This study investigated the association between LRG1 and left ventricular diastolic dysfunction (LVDD)." (PMID 36979923, 2023).
lupus (1 paper, 2020). "However, the exact mechanism needs our further research on lupus and LRG1." (PMID 32252660, 2020).
memory impairment (1 paper, 2022). "Lrg1 overexpression in the brain hippocampal contributes to memory impairment." (PMID 35264055, 2022).
metastatic cancer (1 paper, 2022). A carcinoma which has spread from the original site of growth to another anatomic site. "This study also revealed that the contribution of LRG1 secreted by the vascular compartment is far more important than that synthesised by the liver, and that targeting LRG1 therapeutically may have utility in restricting metastatic cancer." (PMID 35062948, 2022).
metastatic prostate carcinoma (1 paper, 2022). A carcinoma that arises from the prostate gland and has spread to other anatomic sites. "These implicate a significant biological role of LRG1 in inflammation but also several important hallmarks of cancer development and progression, which might shed light on the highly diverse outcomes among patients diagnosed with high-risk and metastatic prostate cancer." (PMID 36500247, 2022).
Neonatal sepsis (1 paper, 2021). Systemic inflammatory response to infection in newborn babies. "Hence, the lower methylation levels observed in the promoters of genes involved in neutrophil activation (i.e., ATP8B4, LRG1, TREM1, PRTN3, S100A8, ELANE, and CD177) illustrates the role of DNAm in innate immunity in neonatal sepsis." (PMID 33659006, 2021).
neovascular age-related macular degeneration (1 paper, 2021). "The level of LRG1 obtained from eyes in patients with neovascular age-related macular degeneration were increased, which indicated the target therapeutic therapy of anti-LRG1 monoclonal antibody." (PMID 35095520, 2021).
neuropathy (1 paper, 2022). A disorder affecting the nervous system that manifests with pain, tingling, numbness, and/or muscle weakness. "Our findings suggest that LRG1 can be a potential new therapeutic option for treating aberrant peripheral blood vessels and neuropathy associated with diabetic complications, such as diabetic ED." (PMID 35562586, 2022).
non-alcoholic steatohepatitis (1 paper, 2022). "As hepatocyte apoptosis contributes to progression of NASH (non-alcoholic steatohepatitis) in NAFLD, further investigation may uncover a hepato-protective role for LRG1 in NAFLD." (PMID 36346018, 2022).
pancreatitis (1 paper, 2018). Inflammation of the pancreas. "Notably, herein the identified CCN2 + PLG+FN+Col4 + CA19.9 panel appeared to have a higher capability in discriminating PDAC from pancreatitis (AUC = 0.94) than the recently proposed TIMP1 + LRG1 + CA19.9 panel (AUC = 0.89)." (PMID 29941541, 2018).
papilloma (1 paper, 2015). A benign epithelial neoplasm that projects above the surrounding epithelial surface and consists of villous or arborescent outgrowths of fibrovascular stroma. "A number of genes related to cancer stem cells were validated by qRT-PCR, including Cxcl12/Sdf-1, Pdgfra, Lgr5, Lrg1, Pecam1/CD31, H19 and Src2, which were all significantly upregulated in Nanog-papillomas and Nanog-SCCs relative to control papillomas." (PMID 25988972, 2015).
periodontal disease (1 paper, 2024). "Excessive inflammatory response in periodontal disease is characterized by bone destruction, similar to RA, the pathophysiology of which also involves LRG1 production." (PMID 38656694, 2024). "This study establishes a correlation between serum LRG1 levels and periodontal disease based on PISA, suggesting its potential as an effective serum marker for evaluating periodontal disease." (PMID 38656694, 2024). "The effect of LRG1 on the progression of periodontal disease was also determined in a mouse model." (PMID 38656694, 2024). "The correlation between LRG1 production in the serum and the degree of periodontal inflammation was evaluated using PISA, and its effectiveness as a periodontal disease test marker was demonstrated in this study." (PMID 38656694, 2024). "Therefore, it remains unclear whether serum LRG1 is effective for evaluating periodontal disease." (PMID 38656694, 2024).
prediabetes (1 paper, 2024). "Reduced adiponectin and nefastin-1 levels in prediabetes were associated with an increased risk of developing DM, whilst leucine-rich alpha-2-glycoprotein 1 (LRG1) expression was related to insulin dysmetabolism." (PMID 38667278, 2024). "Indeed, overexpressed LRG1 was found in obese humans and mice, where it promoted hepatic steatosis, enhancing lipogenesis and suppressing fatty acid β-oxidation, and inhibited IRS1 and IRS2, thus promoting IR and prediabetes." (PMID 38667278, 2024).
primary biliary cirrhosis (1 paper, 2011). "Immunohistochemistry for LRG1 was performed on normal hepatobiliary tissue, benign biliary disease (PSC and primary biliary cirrhosis (PBC)) and BTC to evaluate differential staining characteristics." (PMID 21970875, 2011).
primary cardiomyopathy (1 paper, 2020). "The findings suggest that SDMA, LRG1, SAA, and ceruloplasmin are promising novel biomarkers for CHF caused by primary cardiomyopathy in cats." (PMID 32395893, 2020).
proliferative diabetic retinopathy (1 paper, 2021). Advanced retinopathy due to diabetes mellitus characterized by the formation of new vessels in the retina. "Baseline plasma LRG1 was associated with proliferative diabetic retinopathy, suggesting that it might be a desirable biomarker to predict the late proliferative stage of diabetic retinopathy." (PMID 35095520, 2021). "LRG1 levels in plasma and vitreous were increased in the individuals with proliferative diabetic retinopathy." (PMID 35095520, 2021).
Psoriasiform dermatitis (1 paper, 2024). A skin abnormality characterized by redness and irritation, with thick, red skin that displays flaky, silver-white patches (scales). "EV from primary keratinocytes from the IMQ-treated mice promote IMQ-induced psoriasiform dermatitis, but it is currently unclear whether LRG1 expression in EVs is a major factor." (PMID 38250043, 2024).
psychosis (1 paper, 2024). "At a group level, Complement C8B, C4B, C5, and leucine-rich α-2 glycoprotein 1 (LRG1) were associated with transition to psychosis but did not surpass correction for multiple comparisons." (PMID 38243809, 2024). "C4B, Complement C4-A (C4A), Complement C2 (C2), A2M, LRG1, and the Fibrinogen alpha, beta, and gamma chains (FGA, FGB, and FGG) were differentially expressed between those who transitioned to psychosis and those who did not, adjusting for age, sex, and study." (PMID 38243809, 2024).